DRD1 (dopamine receptor D1)
Diseases named in the same sentence as DRD1 in open-access papers (continued):
Sharing a sentence is not in itself a finding about the gene and the disease.
lung carcinoma (continued). "Furthermore, DRD1 modulates the expression of EGFR and PD‐L1, two molecules that are key drug targets of FDA‐approved and development‐stage therapies in lung cancer and other cancer types, so targeting DRD1 signaling may also be able to augment these therapies." (PMID 38572507, 2024). "Furthermore, dopamine-mediated increases in DRD1 expression have been shown to suppress the proliferation and cytotoxicity of CD4 and CD8 + T lymphocytes in lung cancer patients in vitro." (PMID 34717619, 2021). "Interestingly, PD‐L1 expression was particularly reduced at the cell membrane while PD‐L1 was also observed in the cytoplasm and nucleus in these lung cancer cells, and the nuclear PD‐L1 was not substantially reduced by DRD1 expression." (PMID 38572507, 2024). "Although there were no suitable datasets collected from lung cancer trials, data from two recent clinical trials of nivolumab in advanced melanoma were used to compare patient response to treatment when patients were stratified by level of DRD1 mRNA expression." (PMID 38572507, 2024).
neuroblastoma (5 papers, 2015 to 2025). Neuroblastoma (NB) is the most common solid, extracranial childhood tumor. "Studies have also demonstrated that DRD1 activation is involved in dopamine’s cytotoxic effect on human neuroblastoma cells." (PMID 34717619, 2021).
type 2 diabetes mellitus (5 papers, 2010 to 2024). A type of diabetes mellitus that is characterized by insulin resistance or desensitization and increased blood glucose levels. "The results suggest the potential clinical significance of DRD1 regulation by MIR195-5p in patients with AH and concurrent type 2 diabetes (T2DM)." (PMID 38256676, 2024).
alcohol abuse (4 papers, 2013 to 2022). The use of alcoholic beverages to excess, either on individual occasions ("binge drinking") or as a regular practice. "Among them, two important signal molecules that are related to alcohol abuse have been identified: dopamine receptor D1 (DRD1) and DeltaFosB." (PMID 23873704, 2013). "Szczepankiewicz and colleagues investigated the possible relationship between polymorphisms in the four dopamine receptor genes (−48 A/G in DRD1, −141 C ins/del in DRD2, 9 Ser/Gly in DRD3, and −521 C/T in DRD4) and the comorbidity of alcohol abuse in bipolar patients." (PMID 35893041, 2022). "A significant effect of severity of alcohol abuse on DRD1 expression (P = 0.024) was not confirmed by post hoc tests (the most significant P = 0.053 between controls and alcoholics with severe disorder)." (PMID 29383684, 2018).
glioma (4 papers, 2017 to 2024). A benign or malignant brain and spinal cord tumor that arises from glial cells (astrocytes, oligodendrocytes, ependymal cells). "DRD1 is highly expressed in glioma tumors and mediates tumor growth." (PMID 39387520, 2024). "MiR-21 can promote glioma invasion, and its target DRD1 is related to cancer metastasis." (PMID 29312626, 2017). "Dopamine and its receptor (DRD1–3) are also neurotransmitters that have been associated with increased endometrial cancer severity and reduced progression-free survival, with the DRD2 antagonist ONC201 shown to reduce tumour growth in vivo, including the highly aggressive H3K27M mutant gliomas." (PMID 37371546, 2023).
heroin dependence (4 papers, 2014 to 2025). Physical and psychological dependence on the drug heroin. "Additional systems biology results indicated heroin dependence as the highest-risk manifestation linked to these genes, and PGx analyses suggested DRD1, DRD2, BDNF, and OPRM1 as promising targets for future studies." (PMID 41333412, 2025).
melanoma (4 papers, 2020 to 2025). A malignant, usually aggressive tumor composed of atypical, neoplastic melanocytes. "This principle was supported by our observation that high levels of tumor DRD1 expression was associated with increased response to anti‐PD‐1 therapy in two separate cohorts of melanoma patients." (PMID 38572507, 2024). "When American Joint Committee on Cancer (AJCC) staging was considered, DRD1 was also significantly higher expressed in Stage I tumors than in more progressed melanoma (Padj < 0.05)." (PMID 35053262, 2022). "Following mined data, all dopamine receptors were detected in melanomas; among them DRD1 in 33.8%, DRD2 in 11.3%, DRD3 in 4.5%, DRD4 in 62.4%, and DRD5 24.1% of samples." (PMID 35053262, 2022). "High DRD2 protein expression on tumour cells was observed in 48% of pheochromocytomas, and DRD1 expression ranged from 14% in melanoma to 57% in renal cell carcinoma." (PMID 31478179, 2020). "TAAR8, TAAR9, DRD1, DRD2, and DRD5 expression was also slightly upregulated in melanomas after immunotherapy (Padj < 0.05)." (PMID 35053262, 2022). "DRD1 and DRD2 are expressed in melanoma samples and nondamaged human skin." (PMID 35053262, 2022).
Stroke (4 papers, 2018 to 2021). Sudden impairment of blood flow to a part of the brain due to occlusion or rupture of an artery to the brain. "In consideration of other clinical variables from the multivariable regression model, those with the minor allele of DRD1 (rs4532), with a previous episode of aspiration pneumonia showed the greatest ORs in poor post-stroke swallowing outcome in the elderly age group." (PMID 34276537, 2021). "Finally, while BDNF was associated with improved swallowing outcome in stroke patients in a previous study, DRD1 was shown to be involved with poor outcome in this study, raising the question which SNP is the critical biomarker." (PMID 34276537, 2021). "The presence of the DRD1 polymorphism may play a role in poor swallowing recovery after stroke." (PMID 34276537, 2021). "Furthermore, genes that were regulated differently following stroke in an age-dependent manner showed greater down- (or up-) regulation of gene response to stroke, including genes related to dopaminergic function (Drd1 and Drd2), in younger animals." (PMID 30034335, 2018). "Future studies on SNPs and post-stroke swallowing recovery focusing on the BDNF and DRD1 interactions may be needed." (PMID 34276537, 2021).
Arthritis (3 papers, 2015 to 2025). Inflammation of a joint. "Unlike Drd2−/− CIA mice, Drd1-null CIA mice did not manifest either more severe inflammation of limbs as determined by clinical arthritis score, ankle joint width, and hind paw thickness or higher serum anti-CII IgG level, in comparison with wild-type CIA mice." (PMID 26693483, 2015).
breast tumors (3 papers, 2012 to 2020). "We next sought to address the correlation between CNA frequencies and expression levels of MYC, EGFR, ASAP1, IRF2BP2, CCT5, and DRD1 in broad BC cell lines and breast tumors and the clinical relevance of the genes to patients with BC." (PMID 32235890, 2020). "In contrast, we used molecular cloning and RT-PCR to confirm expression of the DRD1 gene in primary breast tumors and several BCC." (PMID 35582277, 2019). "While CNA events in deep or shallow depletion rarely or less occurred, EGFR, MYC, IRF2BP2, ASAP1, and CCT5 (except for DRD1) often underwent copy gain and amplification, acquiring CNA-driven expression in the breast tumors." (PMID 32235890, 2020). "These genes (except for DRD1) acquired CNG/amplification and high expression in breast tumors." (PMID 32235890, 2020).
insomnia (3 papers, 2021 to 2024). A sleep disorder characterized by difficulty in falling asleep and/or remaining asleep.
liver cancer (3 papers, 2022 to 2024). An epithelial or non-epithelial malignant neoplasm that arises from the liver. "We previously found that DRD1 was highly expressed in liver cancer tissues and the positive expression of DRD1 is associated with unfavorable RFS and OS in HCC patients." (PMID 36091153, 2022). "Discrepant studies have also shown that patients with liver cancer with a high dopamine receptor D1 (DRD1) expression had worse prognosis, and the usage of the DRD1-specific antagonist SCH23390 significantly inhibited cell invasion and migration in vitro and tumor growth in vivo." (PMID 35280754, 2022).
opioid dependence (3 papers, 2013 to 2021). "We propose that DRD1 polymorphism affects susceptibility to opioid dependence (OD), the efficiency of transition to OD, and opioid-induced pleasure response." (PMID 23976958, 2013). "Fewer conclusions can be drawn about DRD1; for example, several DRD1 polymorphisms were initially associated with a rapid transition from first opioid use to opioid dependence, but the results could not be replicated." (PMID 31620026, 2019).
pancreatic cancer (3 papers, 2020 to 2022). "For the other tumour types, high expression of DRD1 on endothelial cells was only observed in 4 out of 14 renal cell carcinomas and 1 pancreatic cancer sample." (PMID 31478179, 2020). "Similarly, DRD1 activation was suggested to be responsible for the enhanced antitumor activities in pancreatic cancer, although, in other tumor types, it behaves contradictorily (i.e., human hepatocellular carcinoma, breast cancer, etc.)." (PMID 36428628, 2022). "It was also established that DRD1 activation might enhance antitumour activities in pancreatic cancer." (PMID 34717619, 2021). "This is true for pancreatic cancer, for which the overexpression of dopamine receptors, particularly DRD2, was found, although some findings suggest a greater role for DRD1 receptors, as it was established that DRD1 activation may enhance antitumor activities in pancreatic cancer." (PMID 36428628, 2022).
sleep disorder (3 papers, 2018 to 2024). A change from the patient's baseline sleeping pattern, in the hours slept and/or an alteration/dysfunction in the stages of sleep. "We mapped the dopamine receptor family DRD1, DRD3, and other targets for improving sleep disorders with the components of AMS to the dopaminergic metabolic signaling pathway and constructed a metabolic pathway map." (PMID 38784223, 2024).
Ventricular arrhythmia (3 papers, 2020 to 2023). "We next investigated whether the overexpression of Drd1 gene is sufficient to trigger ventricular arrhythmia in vivo." (PMID 32868781, 2020).
alcohol addiction (2 papers, 2013 to 2023). "Indeed, alcohol addiction is a complex process in which many genes such as Drd1 and DeltaFosB are involved." (PMID 23873704, 2013).
astrocytoma (2 papers, 2009 to 2020). "Receptor overexpression in rare cancers included 5-HTR1B in nasopharyngeal carcinoma (17%), DRD1 in ependymoma (30%) and synovial sarcoma (21%), and DRD2 in astrocytoma (13%)." (PMID 31478179, 2020).
behavioral disorders (2 papers, 2021 to 2023). "This substitution has been found to be associated with behavioral disorders and possibly also with pathogenesis of PD D1 receptor gene (DRD1) is located at 5q35.1 and has two exons." (PMID 34945793, 2021).
brain injury (2 papers, 2017 to 2026). Acute and chronic (see also brain INJURIES, CHRONIC) injuries to the brain, including the cerebral hemispheres, CEREBELLUM, and brain STEM. "Neurotransmission-related genes (BDNF, COMT, DRD1–3, DBH, SLC6A4, HTR2A, APOE) influenced motivation, fatigue, cognitive performance, and brain injury recovery." (PMID 41596414, 2026). "In this context it is of note that increased mRNA levels of DRD1 and DRD2 in the intestinal mucosa after traumatic brain injury correlated with an impaired intestinal mucosal barrier function." (PMID 28057070, 2017).
cardiac hypertrophy (2 papers, 2020). "The potential role of DRD1 in the development and progression of cardiac hypertrophy remains to be determined." (PMID 32878883, 2020). "DRD1 and GRM1, the genes that were downregulated at all time points, have not previously been linked specifically to cardiac hypertrophy but based on our results may merit further investigation in this context." (PMID 32878883, 2020).
Chorea (2 papers, 2013 to 2025). Chorea (Greek for 'dance') refers to widespread arrhythmic involuntary movements of a forcible, jerky and restless fashion. "In addition, a decrease in the Drd1/Gαolf signal in the striosome compartment in later stages could produce upregulation of dopamine release in the striatum via the striosomal pathways, and if so, this might induce chorea." (PMID 40943492, 2025).
COVID-19 (2 papers, 2023 to 2025). A disease caused by infection with severe acute respiratory syndrome coronavirus 2. "The indirect paths between rumination and DRD1/DRD4 expression in PBMCs were significant only in cohort II, suggesting that cognitive processes, such as repetitive negative thinking, may relate to dopaminergic pathways in recently discharged COVID-19 patients." (PMID 41574058, 2025). "While previous studies suggest that DA can supress NLRP3, leucine-rich repeat (LRR), and pyrin domain-containing protein 3 (NLRP3) inflammasome activation via DRD1 pathways, our findings indicate that DRD4 may not mediate this mechanism in the context of post-COVID-19 recovery." (PMID 41574058, 2025).
dependence (2 papers, 2013 to 2021). "DRD1 polymorphism (rs4532, rs686, and rs265981) has also been associated with substance dependence, addictive behavior, and psychiatric diseases." (PMID 23976958, 2013). "In conclusion, DRD1 rs686 minor allele decreases the OD risk by prolonging the transition to dependence and attenuating opioid-induced pleasure in Chinese." (PMID 23976958, 2013).
eating disorder (2 papers, 2020 to 2024). A broad group of psychological disorders with abnormal eating behaviors leading to physiological effects from overeating or insufficient food intake. "Thus, we believe that miR-504 and miR-16 modulate DRD1 and DRD2, in the context of eating disorders associated with ELS." (PMID 32848865, 2020).
ependymoma (2 papers, 2020 to 2021). A WHO grade II, slow growing tumor of children and young adults, usually located intraventricularly. "One probe for the DRD1 gene exhibited uniform low hybridisation across all ependymoma samples, and a probe for ANGTPL6 showed high expression in both RELA fusion‐positive and RELA fusion‐negative reference samples." (PMID 34314101, 2021). "Overexpression of DRD1 was most frequently found in ependymoma and synovial sarcoma with 46 out of 156 (30%) respectively 7 out of 34 (21%) of the samples." (PMID 31478179, 2020).
pulmonary fibrosis (2 papers, 2024 to 2025). Chronic progressive interstitial lung disorder characterized by the replacement of the lung tissue by connective tissue, leading to progressive dyspnea, respiratory failure, or right heart failure. "Regarding the effect of YAP1 on pulmonary fibrosis, research has shown that the inhibition of YAP/TAZ through dopamine receptor D1 in lung fibroblasts reduces pulmonary fibrosis." (PMID 38945958, 2024).
substance abuse (2 papers, 2011 to 2024). The use of a drug for a reason other than which it was intended or in a manner or in quantities other than directed. "There are five dopamine receptor genes, DRD1, DRD2, DRD3, DRD4, and DRD5, which are mainly related to different risky behaviors like substance abuse and addiction." (PMID 38254998, 2024).
Tourette syndrome (2 papers, 2011 to 2020). A neurologic disorder caused by defective metabolism of the neurotransmitters in the brain. "In the Tourette syndrome group and in smokers there was a significant additive effect of the DRD1 and DRD2 genes." (PMID 22408582, 2011).
triple-negative breast carcinoma (2 papers, 2017 to 2020). An invasive breast carcinoma which is negative for expression of estrogen receptor (ER), progesterone receptor (PR), and human epidermal growth factor receptor 2 (HER2). "In conclusion, we demonstrate that an inhibitory agent of de-phosphorylation of eIF2α through agonizing DRD1 potentially offers a novel therapeutic option for attenuating malignant phenotypes of triple negative breast cancer cells, as well as reducing osteolytic lesions from bone metastasis." (PMID 28374823, 2017).
acute lung injury (1 paper, 2021). A condition of lung damage that is characterized by bilateral pulmonary infiltrates (pulmonary edema) rich in neutrophils, and in the absence of clinical heart failure. "Our results indicated that prophylactic activation of DRD1-dependent signaling pathway exhibited significant protective effects against mechanical stretch-induced endothelial barrier dysfunction and acute lung injury." (PMID 33456556, 2021).
aging (1 paper, 2021). A developmental process that is a deterioration and loss of function over time. "First, we explored the associations between cognitive aging and the dopamine receptor-related loci, including the DRD1, NCAM1-TTC12-ANKK1-DRD2, DRD3-LOC107986115-ZNF80-TIGIT-MIR568-ZBTB20, DRD4, and DRD5-SLC2A9 loci." (PMID 34285142, 2021).
alpha thalassemia/mental retardation syndrome (1 paper, 2019). "For example, Rad54-like subfamily was further classified into four subgroups, namely, Rad54, J-binding protein 2 (JBP2), alpha thalassemia/mental retardation syndrome X-linked (ATRX), and DRD1, containing 2 (SlCHR22 and SlCHR32), 1 (SlCHR25), 1 (SlCHR20), and 10 SlCHRs, respectively." (PMID 31049349, 2019).
amblyopia (1 paper, 2022). Decreased vision that results from abnormal visual development. "The third limitation would be that it is still an open question whether the downregulation of DRD1 is a primary cause of amblyopia or just a downstream consequence of monocular form deprivation." (PMID 35757538, 2022). "This study suggested that the downregulation of DRD1 in the LGN may be a cause for amblyopia." (PMID 35757538, 2022). "Second, this study suggests a specific molecular mechanism of amblyopia, that is, the downregulation of DRD1 in the target region of the form-deprived eye." (PMID 35757538, 2022). "On the other hand, this study also opens the possibility of novel strategies for amblyopia treatment, which means DRD1 in the dLGN can be another target for amblyopia treatment." (PMID 35757538, 2022). "Of these DEGs, DRD1 was confirmed to be downregulated in both primate and rodent amblyopia models." (PMID 35757538, 2022). "Thus, we checked the protein expression of DRD1 in the LGN of the mouse amblyopia model by Western blot." (PMID 35757538, 2022).
anemia (1 paper, 2025). A reduction in the number of red blood cells, the amount of hemoglobin, and/or the volume of packed red blood cells. "Sb showed superiority in reducing anemia and TNF-α and elevating CD4 and DRD1 gene expression and improving brain histopathological alteration compared to dark chocolate." (PMID 40615531, 2025).
Atrophy (1 paper, 2024). Any weakening or degeneration, especially through lack of use. "If the level of DRD1 and DRD2 is insufficient, motor atrophy will be caused." (PMID 40777974, 2024).
brain edema (1 paper, 2018). Increased intracellular or extracellular fluid in brain tissue. "DRD1 antagonist and IFN-beta siRNA reversed effects of A68930 on neurological outcome and brain edema." (PMID 29301581, 2018).
brain tumors (1 paper, 2021). "In summary, this study demonstrates that mechanical loading regulates dopaminergic signaling and remotely suppresses brain tumors by inhibiting the Lrp5-CCN4 axis via DRD1, indicating the possibility of developing an adjuvant bone-mediated loading therapy." (PMID 34031366, 2021).
carcinoma in situ (1 paper, 2024). "Additionally, in a cohort of patients with preinvasive carcinoma in situ (CIS), we observed increased methylation of the DRD1 promoter in preinvasive lesions that progress to LUSC compared to lesions that regress." (PMID 38572507, 2024).
central obesity (1 paper, 2024). "DRD1 and DRD2 gene expression in subcutaneous adipose tissue correlated positively with clinical markers of insulin resistance (e.g. HOMA-IR, insulin, and triglycerides) and central obesity in subjects without T2D." (PMID 37752366, 2024).